MOB4 (MOB family member 4, phocein)
Description:
Part of the striatin-interacting phosphatase and kinase (STRIPAK) complexes. STRIPAK complexes have critical roles in protein (de)phosphorylation and are regulators of multiple signaling pathways including Hippo, MAPK, nuclear receptor and cytoskeleton remodeling. Different types of STRIPAK complexes are involved in a variety of biological processes such as cell growth, differentiation, apoptosis, metabolism and immune regulation.
Synonyms: Mob3; MOBKL3; PHOCN; PREI3; CGI-95; DKFZP564M112; 2C4D; MOB1
Tractability: Antibody: UniProt places it where antibodies can reach, with high confidence. PROTAC: ubiquitination databases record sites on it; its protein half-life has been measured.
Gene: Protein-coding gene on chromosome 2 (197,515,571 to 197,553,699, forward strand). Ensembl gene ENSG00000115540.
Subcellular location: Cytoplasm, perinuclear region; Membrane; Golgi apparatus, Golgi stack membrane
Gene Ontology:
Molecular function: protein binding; protein-macromolecule adaptor activity
Biological process: negative regulation of hippo signaling; regulation of hippo signaling
Cellular component: FAR/SIN/STRIPAK complex; Golgi apparatus; cytoplasm; glutamatergic synapse; Golgi cisterna membrane; membrane; perinuclear region of cytoplasm; postsynapse
Genetic constraint (gnomAD): Loss-of-function variants: 4 observed, 32.01 expected, observed/expected ratio (o/e) 0.12, 90% interval 0.061 to 0.29. The upper end of that interval is the gene's LOEUF score, 0.29, which puts it in group 1 of 6, group 1 being the genes least tolerant of losing a copy. Missense variants: 158 observed, 268.55 expected, observed/expected ratio (o/e) 0.59, 90% interval 0.52 to 0.67. Synonymous variants: 88 observed, 85.24 expected, observed/expected ratio (o/e) 1.03, 90% interval 0.87 to 1.23.
Homologues: Orthologues: chimpanzee MOB4 (100% identical), dog MOB4 (100% identical), mouse Mob4 (100% identical), pig MOBKL3 (100% identical), rat Mob4 (100% identical), guinea pig MOB4 (99% identical), tropical clawed frog mob4 (97% identical), zebrafish mob4 (94% identical), macaque HSPE1 (93% identical), Drosophila melanogaster Mob4 (80% identical), Caenorhabditis elegans mob-4 (67% identical). Paralogues in human: MOB3B (22% identical), MOB1A (21% identical), MOB3A (21% identical), MOB1B (21% identical), MOB2 (21% identical), MOB3C (19% identical).
Diseases named in the same sentence as MOB4 in open-access papers:
MOB4 is named in the same sentence as 11 diseases in open-access papers, as found by Europe PMC text mining. Sharing a sentence is not in itself a finding about the gene and the disease. The quoted sentences say what the papers report.
glioblastoma (2 papers, 2021 to 2023). The most malignant astrocytic tumor (WHO grade IV). "The genes of doxorubicin included the gene MOB Family Member 4 (MOB4) which has been associated with tumor progression in glioblastoma." (PMID 33413081, 2021).
schizophrenia (2 papers, 2021 to 2024). A major psychotic disorder characterized by abnormalities in the perception or expression of reality. "Genes that were associated with brain volumes, depression, and schizophrenia or bipolar disorder includedAC011997.1,AKT3,BANK1,BOLL,DCC,HSPD1,HSPE1,HSPE1-MOB4,MOB4,PLCL1,RFTN2,SF3B1, andTRPS1." (PMID 40800518, 2024).
nemaline myopathy (1 paper, 2022). Nemaline myopathy (NM) encompasses a large spectrum of myopathies characterized by hypotonia, weakness and depressed or absent deep tendon reflexes, with pathologic evidence of nemaline bodies (rods) on muscle biopsy. "In conclusion, mob4 function is required for the incorporation of skeletal muscle α-actin into organised sarcomeres and loss of mob4 function results in aggregates, which share only some aspects of nemaline bodies present in human nemaline myopathy." (PMID 35737712, 2022). "To discover novel molecules involved in thin filament assembly and better understand this process, we initiated a genetic screen in zebrafish that resulted in the identification of mob4-deficient mutants with sarcomeric defects and aggregates that resembled aspects of human nemaline myopathy." (PMID 35737712, 2022).
pancreatic cancer (1 paper, 2020). "For pancreatic cancer, MST4 interacted with MOB4 to form MST4-MOB4 complex, which antagonized MST1-MOB1 complex to positively regulate YAP activity, thus promoting the cell migration and proliferation." (PMID 32742458, 2020).
myopathy (1 paper, 2022). A disease of the muscle in which the muscle fibers do not function properly. "Whereas loss of mob4 led to impaired actin biogenesis and defects in the contractile apparatus assembly, which resembled aspects of human myopathy disorders, gain of mob4 function resulted in a higher amount of contractile apparatus." (PMID 35737712, 2022).
MOB4 also shares sentences with these, for which no sentence is quoted: cancer (2 papers); Alzheimer disease (1); bipolar disorder (1); depression (1); glioma (1); tumor (1).